MYD88 (MYD88 innate immune signal transduction adaptor)
Diseases named in the same sentence as MYD88 in open-access papers (continued):
Sharing a sentence is not in itself a finding about the gene and the disease.
gastroenteritis (1 paper, 2014). An inflammatory disorder that affects the upper and lower gastrointestinal tract. "In contrast, vancomycin pretreatment of mice deficient in SIGIRR (Sigirr−/−), a negative regulator of MyD88-dependent signaling led to heavy and widespread C. jejuni colonization, accompanied by severe gastroenteritis involving strongly elevated transcription of Th1/Th17 cytokines." (PMID 25033044, 2014).
gastrointestinal lymphoma (1 paper, 2025). A non-Hodgkin or Hodgkin lymphoma that arises from any part of the digestive system, with the bulk of the disease localized to that site. "Lachnospiraceae abundantly synthesize butyrate via several intricate metabolic routes, interfering with gastrointestinal lymphoma reinforcing the NF-κB pathway via the MyD88-dependent TLR4 signaling." (PMID 39930533, 2025).
gingivitis (1 paper, 2019). A disorder involving inflammation of the gums; may affect surrounding and supporting structures of the teeth. "In general, genes from both pathways were broadly up-regulated by commensal biofilm and to a lesser extent by gingivitis biofilm whereas cariogenic biofilm only up-regulated two genes in the MyD88-dependent pathway." (PMID 31448244, 2019). "Furthermore, we found that gingivitis biofilm in particular could activate CCL5 (MyD88-dependent and independent) transcription and cariogenic biofilm could activate CXCL10 (MyD88-independent) transcription." (PMID 31448244, 2019). "MyD88, IRAK2, IRAK4 (MyD88-dependent), and TBK1 (MyD88-independent) were significantly up-regulated in RHG exposed to commensal biofilm compared to gingivitis or cariogenic biofilms." (PMID 31448244, 2019).
glaucoma (1 paper, 2021). Increased pressure in the eyeball due to obstruction of the outflow of aqueous humor. "On the other hand, expression of miR-204 in glaucoma and optic nerve injury is high, which by disrupting GAP-43 disrupts the MyD88/TLR4/NFKB pathway and ultimately kills retinal cells (N.)." (PMID 34646884, 2021).
glucose metabolism disorder (1 paper, 2025). "By stimulating the IRS-1/PI3K/AKT signaling system, SE-PP controlled glucose metabolism disorder in adipose tissue, while also inhibiting the TLR4/MYD88/NF-κB pathway to reduce inflammation." (PMID 40941124, 2025).
graft versus host disease (1 paper, 2025). An immune system disorder that occurs after allogeneic hematopoietic stem cell transplant and is a reaction of donor immune cells against host tissues. "However, MyD88 co-stimulation also led to increased, yet non-lethal, graft-versus-host disease (GvHD), indicated by weight loss and inflammation." (PMID 40948803, 2025).
granulocytosis (1 paper, 2021). "Microbiota derived components, such as LPS through TLR4/MyD88 signaling, induced intestinal IL-17 production and increased G-CSF plasma levels leading to granulocytosis." (PMID 33912172, 2021).
hematoma (1 paper, 2022). A hematoma is a collection of blood from a vascular structure into an extravascular space. "We found that there were significant differences in the expression of P38 MAPK (F = 7.429, p = 0.002), MyD88 (F = 6.973, p = 0.002), HMGB1 (F = 11.753, p < 0.001), and IL-1β (F = 6.821, p = 0.002) around hematoma among the four groups (n = 6 mice/group)." (PMID 35242275, 2022). "The expression level of P38-mitogen-protein kinase (P38-MAPK), myeloid differentiation factor 88 (MyD88), high-mobility group box1 protein (HMGB1), and interleukin-1β (IL-1β) around hematoma was examined by western blotting at 24 h." (PMID 35242275, 2022). "ICH elevated the expression of P38 MAPK, MyD88, HMGB1, and IL-1β around the hematoma when compared with sham surgery at 24 h after ICH or sham surgery (all p < 0.05)." (PMID 35242275, 2022). "We detected the effects of choline diet on the relative expression of P38 MAPK, MyD88, HMGB1, and IL-1β around the hematoma with western blot analysis at 24 h after ICH or sham surgery." (PMID 35242275, 2022).
hemorrhagic fever (1 paper, 2015). An infectious disease caused by certain viruses or bacteria that can damage the walls of tiny blood vessels, making them leak, and can hamper the blood's ability to clot and cause severe, life-threatening illness. "SNPs significantly associated with eye disease included three different polymorphisms TLR8 and hemorrhagic fever symptoms associated with TLR3, TLR7, TLR8 and MyD88." (PMID 25756647, 2015).
Herpes simplex infection (1 paper, 2022). "The KEGG pathway analysis highlighted that a large number of genes that were up-regulated after infection with V2 were the same as those upregulated in response to Herpes simplex infection (genes Myd88, Irf7, H2-Q7, Casp8, Tlr3, Daxx, C3, H2-Aa, Oas2, Oas3, H2-T22, H2-T23 and Cd74)." (PMID 35458422, 2022).
hip osteoarthritis (1 paper, 2024). "Necrotic bone tissues from GONFH patients contained a significantly increased macrophage M1/M2 ratio, and higher levels of TLR4, MYD88 and NF‐κB p65 than bone tissues from patients with hip osteoarthritis." (PMID 39123292, 2024).
histiocytic sarcoma (1 paper, 2014). An aggressive malignant neoplasm with a poor response to therapy, usually presenting as stage III/IV disease. "However, the cell infiltrate in the mice of this report were negative on immunohistochemistry for B cell and T cell markers and were positive for macrophage markers and, to our knowledge, activating mutations in MyD88 have not been described in human or murine histiocytic sarcomas." (PMID 25229618, 2014).
interstitial lung disease (1 paper, 2022). A diverse group of lung diseases that affect the lung parenchyma. "MyD88 splicing in PBMCs was also shifted in a pro-inflammatory direction in patients with Interstitial Lung Disease (ILD) who were undergoing an acute exacerbation." (PMID 36531997, 2022).
intestinal type adenocarcinoma (1 paper, 2020). An adenocarcinoma arising from epithelium which has undergone intestinal metaplasia. "What's more, overexpression of MyD88 was detected in intestinal-type adenocarcinoma with inflammation." (PMID 32477927, 2020). "Our observation suggested that MyD88 pathway plays more important role in intestinal-type adenocarcinoma and might be responsible for the inflammatory response and carcinogenesis of this type of adenocarcinoma." (PMID 32477927, 2020). "Moreover, the stronger MyD88 staining was found in intestinal-type adenocarcinoma with severe inflammation than in diffuse-type cancer." (PMID 32477927, 2020).
keloid (1 paper, 2024). An irregularly shaped, elevated mark on the skin caused by deposits of excessive amounts of collagen during wound healing. "Moreover, HIF-1α triggers both the TGF-β/Smad and TLR4/MyD88/NF-κB signaling pathways, and the synergy between these pathways could facilitate keloid formation, and selective HIF-1α inhibitors consistently lead to a reduction in collagen levels." (PMID 39114830, 2024).
kidney damage (1 paper, 2022). "The present experiment corroborates these claims, and it also implies that QB may be able to inhibit the HMGB1/TLR4/MyD88 pathway, thereby reduce autoantibody production, inhibit the release of inflammatory factors, and improve kidney damage." (PMID 35571092, 2022).
kidney transplant (1 paper, 2019). A surgical procedure in which one or both kidneys from a donor are implanted into a recipient. "Notably, SNPs in CASP1, CRP, IL6R, MYD88, and TLR2 have not been examined for their impact on acute rejection in kidney transplant recipients." (PMID 32153387, 2019).
Klebsiella pneumonia (1 paper, 2014). An pneumonia caused by infection with Klebsiella. "Our results suggest that myeloid MyD88 deficiency results in enhanced lethality during Klebsiella pneumonia by a mechanism that involves a strongly attenuated early inflammatory response at the primary site of infection and as a consequence thereof uncontrolled bacterial growth." (PMID 25254554, 2014). "Hence, these data suggest that LysM-Myd88−/− mice replicate the phenotype of Myd88−/− mice with regard to impaired neutrophil influx in the airways during early Klebsiella pneumonia at least in part caused by a reduced chemotactic gradient due to impaired chemoattractant production." (PMID 25254554, 2014).
laryngeal squamous cell carcinoma (1 paper, 2026). A squamous cell carcinoma that arises from the larynx. "This study aimed to evaluate the association of TLR4 (rs7037225, rs11536889, rs7037117) and MYD88 (rs7744, rs6853) polymorphisms with the risk of laryngeal squamous cell carcinoma (LSCC), as well as its clinical and pathological characteristics and survival." (PMID 42278290, 2026).
latent infection (1 paper, 2010). "The specific roles of MAVS in lytic replication and MyD88 in latent infection are consistent with their distinct functions in innate immune responses of epithelial cells and immune cells, respectively." (PMID 20686657, 2010). "Given that MyD88 also activates the IKKα/β kinase complex, it is possible that IKKβ-dependent activation of RTA may contribute to γHV68 and KSHV latent infection as well." (PMID 20686657, 2010).
leukopenia (1 paper, 2015). "It is worth mentioning that the deletion of the TLR2, TLR9 or MyD88 genes did not seem to affect the irinotecan-induced cytotoxic effects because the leukopenia was still observed." (PMID 26440613, 2015).
limb ischemia (1 paper, 2014). A ischemia that involves the limb. "This study adds to our previous findings by demonstrating how TRIF and MyD88 may be required to promote inflammation and recovery after limb ischemia." (PMID 24844636, 2014). "On the basis of our previous findings, we hypothesized that TRIF and MyD88 mediate opposing responses to limb ischemia." (PMID 24844636, 2014). "We describe opposing roles of MyD88 and TRIF, both downstream signaling molecules of TLR4, in the inflammatory and regenerative processes that follow limb ischemia." (PMID 24844636, 2014).
lipidosis (1 paper, 2015). "The results of the present study showed that TLR4 signalling activated the MyD88/NF-κB and the TRIF/IRF3 pathway to elicit lung inflammation and lipidosis in the ApoE−/− WD mice." (PMID 25975841, 2015).
liver dysfunction (1 paper, 2023). "MyD88 is one of the most important adaptor proteins in TLR signaling, and when MyD88 knockout mice are fed a high-fat chow diet, insulin and cholesterol levels increase and liver dysfunction appears, which are all associated with T2DM and NAFLD31." (PMID 37957232, 2023).
Lm (1 paper, 2011). "In agreement to the published data, TNF production was induced upon wild type Lm and Δhly-Lm infection in WT BMDMs and completely abolished in MyD88−/− BMDM, while bacterial uptake in cells of both genotypes was comparable." (PMID 22114673, 2011). "To investigate whether this response is regulated via the TLR signalling pathway and establish the effect of vacuolar infection to the host miRNA response, we compared miRNA induction between WT and MyD88−/− BMDMs, upon wt-Lm and Δhly-Lm infections." (PMID 22114673, 2011).
Mm (1 paper, 2021). "In line with previous results obtained using a systemic infection model, localized Mm infection in the tail fin of myd88-/- larvae results in an increased bacterial burden." (PMID 33559740, 2021).
mononeuropathy (1 paper, 2013). Disease or trauma involving a single peripheral nerve in isolation, or out of proportion to evidence of diffuse peripheral nerve dysfunction. "In the following study, we have extended this systematic assessment of the roles of individual spinal TLRs and the MyD88 and TRIF adaptor proteins in tactile allodynia and surrogate marker activation associated with the L5 SNL mononeuropathy model in male mice." (PMID 24321498, 2013).
mucinous tumours (1 paper, 2014). "In contrast all borderline mucinous tumours were MyD88 negative." (PMID 24977712, 2014).
Mycobacterium avium infection (1 paper, 2021). "Induce Pro-inflammatory responses dependent on TLR 2, TLR4, and MyD88 in Mycobacterium avium infection." (PMID 35058912, 2021).
Mycoplasma infection (1 paper, 2020). "TLR2/MyD88 signaling induces PGE2 production by COX-2 transcription via NF-κB, during not only Mycoplasma infection but also other bacterial infection such as Mycobacterium bovis, Mycobacterium leprae, and Staphylococcus aureus." (PMID 32154274, 2020).
myeloid leukemia (1 paper, 2022). A clonal proliferation of myeloid cells and their precursors in the bone marrow, peripheral blood, and spleen. "Interestingly, MYD88 splicing is not affected in the myeloid leukemia cell line K562 upon splicing factor knockdown, indicating that the splicing of other TLR signaling genes is promoting the increased inflammatory cytokine production in this cell type." (PMID 34196950, 2022).
myxoma (1 paper, 2012). A benign soft tissue neoplasm characterized by the presence of spindle and stellate cells, lobulated growth pattern, and myxoid stroma formation. "In contrast, myxoma-induced type I IFN induction was abolished in MyD88−/−, or TLR9−/− pDCs, but modestly reduced in TLR7−/− pDCs." (PMID 22606294, 2012).
nematode infections (1 paper, 2018). "Using RNA-seq, we consistently found upregulation of Myd88, Wgn, Dome, Daw, and Dpp genes in larvae responding to axenic nematodes compared to symbiotic nematode infections." (PMID 29419764, 2018).
neuritis (1 paper, 2018). A neuropathy arising from inflammation of one or more nerves. "Therefore, the expressions of MyD88, NF‐κB, and TNF‐α reflect the severity of neuritis and the expression of the HMGB1–TLR4 axis." (PMID 29670828, 2018).
neuroblastoma (1 paper, 2006). Neuroblastoma (NB) is the most common solid, extracranial childhood tumor. "NB-1 neuroblastoma cells express TLR4, MD2, CD14 and MyD88, which are required for LPS signaling." (PMID 17156435, 2006).
oral epithelial dysplasia (1 paper, 2020). "Clinical studies have shown a significantly higher expression of TLR4 and MyD88 in oral epithelial dysplasia and OSCC." (PMID 33002094, 2020).
orchitis (1 paper, 2024). Inflammation of one or both testes due to viral or bacterial infections. "OXY could also decrease pro-inflammatory cytokines levels and boost anti-inflammatory by downregulating TLR4, MyD88, NF-κB, and PK2/PKR1 pathways, which are linked to LPS-induced orchitis." (PMID 39845795, 2024).
Osteopenia (1 paper, 2018). Osteopenia is a term to define bone density that is not normal but also not as low as osteoporosis. "Bone histomorphometry revealed that MyD88-deficient (MyD88-/-) mice exhibited typical osteopenia with reduced bone resorption and formation." (PMID 29995146, 2018).
otitis (1 paper, 2015). "Susceptibility to otitis might also be impacted by deficiencies in innate immune molecules, such as the microbial pattern recognition receptors Toll-like receptor 4 (TLR4) and Toll-like receptor 2 (TLR2), and the immune signaling molecule MyD88." (PMID 25765466, 2015).
ovarian epithelial tumor (1 paper, 2019). A benign, borderline, or malignant tumor that originates from the surface epithelium of the ovary. "The activation of TLR, especially via MyD88, is associated with increased tumor growth, chemoresistance, and the early recurrence of ovarian epithelial tumors." (PMID 31861351, 2019).
pancreatitis (1 paper, 2025). Inflammation of the pancreas. "Previous studies reported that quercetin intervention exerted therapeutic effects on pancreatitis, intestinal injury and inflammation by inhibiting the activation of TLR4/MyD88/P38 MAPK pathway by up-regulating miR-216b and endoplasmic reticulum stress." (PMID 39946409, 2025).
Paraproteinemia (1 paper, 2022). An abnormal immunoglobulin or part of an Ig (light chain) in the circulation. "The analyses performed on vitreal body should be combined with other diagnostic techniques and methods that may be necessary in the clinical context (e.g., detection of paraproteinemia in MYD88-mutated cases)." (PMID 35200564, 2022).
pheochromocytoma (1 paper, 2020). "A recent study has found that ferulic acid inhibits TLR4/MyD88 signaling in pheochromocytoma cells through an effect that is abrogated by MyD88 over-expression." (PMID 32455532, 2020).
pituitary adenoma (1 paper, 2022). "A MYD88 p.D210N variant of unknown significance (VUS) with LOH was detected in the M6 aggressive pituitary adenoma." (PMID 35978432, 2022).
plasma cell neoplasm (1 paper, 2025). A clonal proliferation of immunoglobulin-secreting plasma cells. "Biopsy revealed a kappa-restricted plasma cell neoplasm with strong CD138, BCL2, CD20, and PAX5 expression and absence of MYD88 L265P mutation via immunohistochemistry." (PMID 41346800, 2025).
plasmacytoma (1 paper, 2025). Plasmacytoma is a localized mass of neoplastic monoclonal plasma cells that represents approximately 5% of all plasma cell neoplasms. "In contrast, solitary plasmacytomas consist of mature plasma cells, usually lack MYD88 mutations, and exhibit strong CD138 expression without significant lymphoid components." (PMID 41346800, 2025). "In our patient, the absence of MYD88 mutation, lack of marrow infiltration, and presence of mature plasma cell morphology with strong CD138 expression supported plasmacytoma over WM." (PMID 41346800, 2025).
Pleural effusion (1 paper, 2020). The presence of an excessive amount of fluid in the pleural cavity. "Our case of an untreated patient with WM/LPL and EM pleural effusion is the first documented case with pleural fluid MYD88 L265P mutation status in a community hospital setting." (PMID 32654665, 2020). "Our case of a patient with untreated WM/LPL with EM pleural effusion is the first documented case with pleural fluid MYD88 L265P mutation status in a community hospital setting." (PMID 32654665, 2020).
pneumonic plague (1 paper, 2019). A plague in which the bacteria have infected the lungs. "In this work, we sought to identify the host factors that mediate this process and studied the role of the Toll/interleukin 1 (IL-1) receptor adapter and major inflammatory mediator myeloid differentiation primary response 88 (MyD88) in pneumonic plague." (PMID 30642901, 2019).
Pneumovirus Infections (1 paper, 2017). Infections with viruses of the genus PNEUMOVIRUS, family PARAMYXOVIRIDAE. "Nevertheless our findings that IPS-1 signalling is required to increase pDCs in the lung provides a possible mechanism to explain the non-redundant role of both the RLR/IPS-1 signalling and TLR7/MyD88 signalling in the generation of optimal host defence against pneumovirus infection." (PMID 28539639, 2017).
poliovirus infection (1 paper, 2020). An disease or disorder caused by infection with Enterovirus C. "In crab, the miR-7 could inhibit host anti-viral immune response by targeting Myd88 to enhance WSSV replication, whereas the miR-7 up-regulation induced the inhibition of poliovirus infection in human cells." (PMID 33069243, 2020).
preeclampsia (1 paper, 2020). Preeclampsia is a hypertensive disorder of pregnancy that is characterized by new-onset hypertension with proteinuria presenting after 20 weeks of gestation, and depending on mild or severe forms may initially present with severe headache, visual disturbances, and hyperreflexia. "The results of the present study showed that preeclampsia‐induced apoptosis of placental cells was effectively inhibited after Gas treatment, and the underlying mechanism may involve downregulated activity of MyD88/NF‐κB signaling pathway." (PMID 32148791, 2020).
pregnancy disorder (1 paper, 2021). A disorder that is related to pregnancy. "Further studies are undergoing to confirm the relevance of the MyD88-dependent LPS/Tlr4 pathway in inducing LPS-induced defects at the EBIS such that therapies targeted at blocking LPS signaling for the management of infection-induced early pregnancy disorders can be found." (PMID 34360700, 2021).